STAT3 (signal transducer and activator of transcription 3)
Diseases named in the same sentence as STAT3 in open-access papers (continued):
Sharing a sentence is not in itself a finding about the gene and the disease.
tumor (continued). "Activated STAT3 levels in tissues are also related to reduced tumor invasion, tumor, lymph node, metastatic stage, and overall survival in CRC patients." (PMID 39434880, 2024). "In contrast, other studies have found that bone-marrow-derived MSCs reduce cytokines and STAT3 activation, indicating a tumor supporessive role." (PMID 38680862, 2024). "Tumor-derived PGE2 directly induced M-MDSCs to express CD73 through STAT3 and CREB, which suppressed the effect of ICIs." (PMID 39188712, 2024). "One such example is in the case of iCCA, in which TAN–TAM cross-talk mediated by oncostatin M and IL-11 has been shown to enhance the proliferation and aggression of the tumor though STAT3 signaling." (PMID 38730724, 2024). "On the one hand, lncRNAs such as FAL1, FEZF1-AS1, PVT1, and RP11-334E6.12 can upregulate STAT3 expression by binding to the STAT3 promoter and inducing STAT3 phosphorylation, thereby directly inducing tumor cell proliferation and inhibiting apoptosis." (PMID 38172648, 2024). "STAT3 is one of the most well-described STATs members and which mainly acts as tumor promoting roles in tumor development and progression." (PMID 38245798, 2024). "A pivotal role in the generation of PMN-MDSCs is ascribed to the downregulation of IRF8 in hematopoietic progenitor cells, as it induces PMN-MDSC generation and participates in STAT3/STAT5-mediated anti-tumor processes." (PMID 38720342, 2024). "Mifamurtide switches macrophage polarization to a TAM-like intermediate M1/M2 phenotype and reduces IL-17R levels and STAT3 activation, thereby inhibiting cell growth and inducing tumor-cell differentiation." (PMID 39199574, 2024). "STAT3 enhances aggressive tumor phenotypes through pathways, such as epithelial‐mesenchymal transition, radiation‐induced bystander effects, and alterations in the tumor microenvironment following RT." (PMID 38967145, 2024). "In preclinical studies using a nude mouse model, garcinol significantly suppresses HCC tumor growth by suppressing expression of p-STAT3 in garcinol treated tumor tissues." (PMID 39066940, 2024). "STAT3 activation, acting as a convergence point for multiple oncogenic signalling pathways, can lead to the abnormal transcription of genes involved in tumour cell growth, apoptosis, and resistance to chemotherapy." (PMID 39679367, 2024). "Gemcitabine, an inhibitor of topoisomerase I, serves as a first-line adjuvant chemotherapy for advanced PDAC while STAT3, a transcription factor associated with CSC renewal, interacts with the CD44 receptor overexpressed in tumor cells." (PMID 38474109, 2024). "Studies have unveiled its ability to induce tumor cell apoptosis through the Janus kinase 2 (JAK2)/signal transducer and activator of transcription 3 (STAT3)/cyclin-dependent kinase inhibitory protein-1 (p21) pathway and the JNK1 signaling pathway." (PMID 39684655, 2024). "BP1003 penetrates into PDAC PDXs, suppresses STAT3 expression, and induces tumor regression when combined with gemcitabine." (PMID 39200368, 2024). "STAT3 plays a crucial role in the carcinogenesis and tumor progression of various solid tumors, including head and neck squamous cell carcinoma and CRC, as well as leukemias and lymphomas." (PMID 38799159, 2024). "IL-6 facilitates inflammatory reactions and the formation of the tumor microenvironment by activating the JAK/STAT3 signaling pathway, which aids in tumor growth and immune evasion." (PMID 38711918, 2024). "Activated STAT3 contributes to tumorigenesis by promoting cell proliferation and impairing host tumor immunity." (PMID 38238515, 2024). "Analysis of whole tumor protein lysates by Western blots demonstrated reduced levels of total and phosphorylated Yap1 and Stat3 in Gp130FF; Yap1KO compared with Gp130FF; Yap1WT mice." (PMID 37957015, 2024). "On the one hand, CHRNA5 can activate multiple signalling pathways, such as TGF-β1–Smad, JAK2/STAT3 and Notch1, thus promoting tumour cell proliferation, survival and metastasis." (PMID 38879667, 2024).
tumor (continued). "TAM+/TIL+ tumors featured activation of MET and STAT3 signaling, increased stress response, tumor inflammation, senescence and activation of microglia and astrocytes but also activated interferon signaling." (PMID 38386085, 2024). "IL-6R ultimately promotes the expression of STAT3, forming a STAT3/miRNA/IL-6R feedback loop, promoting tumor cell invasion and migration." (PMID 38172648, 2024). "The phosphor-STAT3 staining of untreated SW480 tumor cells scored approximately 50 via a semi-quantitative analysis, which was significantly different from the treated group, with a score of 23 (p < 0.01)." (PMID 38256960, 2024). "Oncogene-induced STAT3 activation plays a central role in tumour progression by amplifying immunosuppressive activity in infiltrating TAMs." (PMID 38183060, 2024). "We further validated that the representative core genes in the IL-6/JAK/STAT3 pathway (Il6st (Gp130), Fas and Stat1) and the late response of estrogen (St6gal, Areg and Serpina3) were highly reduced in shMCT-1 tumor when compared to scramble tumor." (PMID 38505617, 2024). "Therapeutic strategies require a nuanced approach that accounts for the multifaceted physiologic role of STAT3, in addition to its potential tumor-specific dual function as an oncologic driver and tumor suppressor." (PMID 38339245, 2024). "In tumor cells, IL-6-induced activation of Stat3 was increased or maintained by activation of the epidermal growth factor receptor (EGFR)." (PMID 39000275, 2024). "In TNBC patients, the micropeptide ASRPS inhibited tumor angiogenesis by modulating the STAT3/VEGF pathway, and intratumoral injection of ASRPS also prolonged the survival time in TNBC mouse models." (PMID 38622617, 2024). "Together, these findings suggest that regulatory T cells infiltrate glioblastoma tumors, promoting the TGF beta, TNF via NF-kB, and IL6/JAK/STAT3 signaling pathways and thereby increasing mesenchymal transition of tumor cells." (PMID 38981682, 2024). "In vitro and in vivo studies have confirmed that pY705 modification of STAT3 is necessary for tumor growth, autophagy, and metastasis and suggest that STAT3 is an effective approach for treating cancer." (PMID 39411137, 2024). "Our findings provide evidence that loss of JUN accompanied by reduced activation of STAT3 bypasses SASP and subsequently amplifies the tumor load in JunPEΔ/Δ; PtenPEΔ/Δ animals." (PMID 38811984, 2024). "Ablating STAT3 in engineering CD8+ T cells results in enhanced tumor antigen-specific T cell activity and tumor growth inhibition." (PMID 38245798, 2024). "In general, protein kinases PKA-Cα and AMPK-α1 play a critical role in regulating the IL-6/STAT3 signaling pathway and the growth and apoptosis of tumor cells." (PMID 39845783, 2024). "Research has increasingly demonstrated that JAK/STAT3 participates in tumor angiogenesis, particularly in the regulation of VEGFA." (PMID 39596828, 2024). "Curcumol reduces the protein levels of HIF-1α and VEGF in the tumor tissues and inhibits crosstalk between STAT3 and HIF-1α pathways, thereby restricting tumor growth and progression." (PMID 39690423, 2024). "MDSCs can also promote tumor metastasis by enhancing β-adrenergic signaling and the IL-6/STAT3 pathway." (PMID 38464516, 2024). "The regulation of PD-L1 expression is complex, involving pathways like IL-6/JAK/STAT3, which are pivotal for maintaining an immunosuppressive tumor microenvironment." (PMID 38473415, 2024). "For instance, M9S1 extracted from Moringa oleifera significantly downregulated the expression of ZIP6 in MDA-MB-231 tumor, treatment with STAT3 inhibitor peptide, cell-permeable (#573096, Sigma)." (PMID 38169461, 2024). "Previous study demonstrated that the knockout of caspases, nucleases and ATM significantly deceases the phosphorylation of STAT3, the expression of stem cell marker, and reduces the ability of tumor spheres formation." (PMID 38977663, 2024).
tumor (continued). "As more and more credible evidence continues to emerge, the clinical application potential of the JAK2/STAT3 therapy has also gradually garnered significant attention in the treatment of chronic pain, such as osteoarthritis (OA) and tumor pain." (PMID 37307838, 2024). "In cancer, nuclear HO-1 affects the JAK-STAT3 pathway by modulating STAT3 activity, impacting tumor growth and survival pathways." (PMID 38915448, 2024). "Follow-up studies are needed to demonstrate the contribution of Stat3 silencing in the tumor cells in enhancing the efficacies of ICB in A20 tumor model." (PMID 39618825, 2024). "Signal transducer and activator of transcription 3 (STAT3), known as a transcription factor, can play a role in promoting tumor by inhibiting anti-tumor immune response." (PMID 37588193, 2024). "Transcription factor activity assays revealed that the new inhibitors effectively blocked the activity of NF-κB, HIF1α, and STAT3 in PDAC tumor cells, with dose-dependent reductions in transcription factor activity observed." (PMID 39635662, 2024). "Overall, it is a well‐planned and refined study that comprehensively demonstrated TMEM25 as a tumor suppressor protein that prevents the interaction of monomeric EGFR with STAT3 and thereby suppresses STAT3 phosphorylation and tumor progression." (PMID 38532948, 2024). "The most important fact of NF-κB and STAT3 is to regulate the expression of cytokines chemokines and chemoattractants which act in the recruitment and renewal of different cells in the tumor microenvironment." (PMID 39493763, 2024). "In conjunction with YTH N6-methyladenosine RNA Binding Protein 1 (YTHDF1), METTL3 mediates m6A modification on JAK1 mRNA, enhancing JAK1 and STAT3 expression and promoting tumor immune escape." (PMID 39659524, 2024). "In vivo, STAT3 phosphorylation is largely present in macrophage populations within the tumor microenvironment." (PMID 38274367, 2024). "As a key transcription factor, signal transducer and activator of transcription 3 (STAT3) has a significant effect on tumor cell proliferation and metastasis." (PMID 38183094, 2024). "The widespread activation of STAT3 in tumor-infiltrating immune cells weakens innate and adaptive immune responses and facilitates immune evasion." (PMID 39309860, 2024). "Increased infiltration and activation of CD8+ T cells in STAT3 inhibited tumours, in comparison to genetic inhibition of pSTAT3+myMAFs alone, suggests an additive effect, likely mediated by the additional suppression of cancer-cell derived Osteopontin." (PMID 38678021, 2024). "STAT3 increases the expression of genes that regulate cell proliferation and survival, leading to uncontrolled tumor growth and drug resistance." (PMID 39153914, 2024). "Interleukin-6 (IL-6), derived from cancer-associated fibroblasts (CAFs), plays a crucial role in initiating the activation of the STAT3 pathway in tumor-infiltrating neutrophils, known as TANs." (PMID 39420203, 2024). "HIF-1α promotes TAMs differentiating from some MDSCs, inhibiting anti-tumor immunity by downregulating STAT3." (PMID 38720342, 2024). "Introducing STAT3 into the tibialis anterior of tumor-bearing mice using a plasmid as a vector resulted in noticeable muscle atrophy." (PMID 38828409, 2024). "Depending on the pathway, these drugs can upregulate the expression of PD-L1 by activating different signaling pathways (such as RAS/RAF, PI3K/AKT, JAK/STAT3) and release specific immunosuppressive cytokines, thus weakening the anti-tumor immune response." (PMID 38333217, 2024). "We previously demonstrated that CD44+CD24− cancer cells are enriched in basal-like tumors compared with other breast cancer subtypes and that CD44+CD24− cancer cells have heightened IL-6/JAK2/STAT3 signaling activity compared with other tumor cells." (PMID 38297352, 2024). "Cantharidin is another anti-tumor compound in treatment of HCC that suppresses STAT3 and PI3K/Akt pathways in reducing survival rate and colony formation of tumor cells." (PMID 38997297, 2024).
tumor (continued). "Similar results were observed in prostate cancer where gut dysbiosis increased gut permeability and intratumoral LPS which promotes tumor progression via NF-κB/IL6/STAT3 axis." (PMID 38520006, 2024). "On the other hand, excessive activation of STAT3 in the malignant tumor microenvironment has been suggested to induce immunosuppression." (PMID 39367511, 2024). "Although the role of STAT3 as an oncogene has been well demonstrated, with many cancers harboring constitutively active STAT3, some studies suggest that STAT3 has a context-dependent tumor suppressor role." (PMID 38339245, 2024). "IL17A augments IL6 production by activating tumor-intrinsic STAT3, resulting in tumor growth and invasion." (PMID 38672199, 2024). "These include exosome-containing oncogenic proteins, such as STAT3 and FAS, microRNAs that altered tumor-associated macrophages, as well as plasma gelsolin, which induces the conversion of chemosensitive OC cells to chemoresistant cells." (PMID 38403587, 2024). "Since IFN-β suppresses the activity of STAT3, IFN-β–deficient mice display more neutrophils with higher levels of VEGF and MMP9, both regulated by STAT3, thus promoting tumor growth." (PMID 38245798, 2024). "IL-6 regulates tumour proliferation and differentiation mainly by mediating the IL-6/STAT3 signaling pathway." (PMID 38613794, 2024). "The expression of IL-6 was lower in tumor tissues (N = 91) compared with normal tissues (N = 31) (P = 0.049), whereas the expression of STAT3 was higher (P = 0.040)." (PMID 38881895, 2024). "In tumour cell metabolic reprogramming, the STAT3/LINC00671/LDHA axis regulates glycolysis, growth and metastasis in PTC." (PMID 39187514, 2024). "IL-22 is involved in the development of tumor diseases, the excess presence of IL-22 in the tumor microenvironment promotes tumor growth, inhibits apoptosis, and facilitates metastasis via STAT3 pathway activation." (PMID 38879568, 2024). "While JAK inhibitors can decrease STAT3 tyrosine phosphorylation in tumor cells, this approach suffers from two major shortcomings." (PMID 38611065, 2024). "IL-17 induces EMT in quiescent gastric CSCs, significantly enhancing their invasion, migration, and tumor formation capabilities while promoting the activation of the downstream phosphorylation signaling pathway of the transcription factor STAT3." (PMID 39676857, 2024). "SD-91 is another STAT3 degrader that is capable of achieving complete and long-lasting tumor regression in xenograft models of megakaryoblastic leukemia." (PMID 38611065, 2024). "Recent, in vivo evidence on GC showed that IL-6/STAT3 signaling can be activated in the tumor environment through persistent inflammation." (PMID 39456519, 2024). "Inhibition of STAT3 potentiated responses to PI3K inhibitor in vitro and in vivo, durably suppressing tumor growth, increasing apoptosis, and causing marked tumor regression." (PMID 39068158, 2024). "CSCs have the ability to release interleukin-6 (IL-6), triggering the activation of STAT3 signaling in tumor cells and promoting tumor growth." (PMID 38926605, 2024). "Targeting STAT3 offers therapeutic advantages by suppressing tumor proliferation and enhancing anti-tumor immune responses." (PMID 39056720, 2024). "Many studies have shown that STAT3 activation in tumor cells governs the secretion of diverse pro-inflammatory factors including IL-6, IL-10 and VEGF." (PMID 38245798, 2024). "Many preclinical studies have informed the critical role of STAT3 activation in malignant transformation using tumor-derived cell lines, thus, STAT3 is considered by most to be an oncogene." (PMID 38339245, 2024). "As a critical member of the signal transducer and activator of transcription (STAT) family, STAT3 participates in tumor cell proliferation, differentiation, and apoptosis." (PMID 38962311, 2024). "Taken together, the data convincingly showed that high expression of MUC1 in multiple tumor types sensitizes the cells to the STAT3 inhibitor Napabucasin." (PMID 38326371, 2024).
tumor (continued). "In the case of carcinogen-induced tumorigenesis, STAT3 has an inhibitory effect on tumor NK cell immunity and induces subsequent immune exclusion." (PMID 38693304, 2024). "These phosphorylated STAT3 dimers subsequently enter the nucleus and bind to DNA, activating target genes that regulate tumor cell proliferation, angiogenesis, metastasis, and anti-apoptotic responses." (PMID 39153914, 2024). "The EGFR/STAT3 signal axis is a relatively well-defined cytokine and growth factor signal axis, and STAT3 has long since been shown to promote tumor growth." (PMID 39338323, 2024). "For example, studies reported that the STAT3β isoform mediates the tumor suppressor effects of STAT3 by forming a heterodimer with STAT3α, thereby inhibiting the transactivation of STAT3α." (PMID 38339245, 2024). "It has been postulated that LIFR signaling promotes tumor dormancy specifically through STAT3 activation; however, the oncogenic ERK and AKT pathways can still be activated by LIFR-binding cytokines." (PMID 38409028, 2024). "Drugs that inhibit upstream activators of STAT3, i.e. inhibitors of the IL-6 family of cytokines, represent a promising therapeutic strategy to curb tumour growth." (PMID 38600086, 2024). "In this regard, the blockade of NF-κB with pentoxifylline (PTX) or STAT-3 with Stattic (STT) is known to increase the sensitivity of tumor cells to chemotherapy in both in vitro and in vivo models." (PMID 39329957, 2024). "We found that the expression of IL-6 was lower, while the expression of STAT3 was higher in tumor tissues using mIF." (PMID 38881895, 2024). "The results revealed that the expression of IL-6 was lower, while the expression of STAT3 was higher in tumor tissues compared to normal tissues." (PMID 38881895, 2024). "The correlation between STAT3 expression and the infiltration of multiple immune cells indicated its possible involvement in the regulation of the tumor immune microenvironment." (PMID 39132168, 2024). "Vascular endothelial growth factor (VEGF), which is among the target of STAT3, also contributes to tumor angiogenesis." (PMID 38975347, 2024). "Proteomics investigation revealed that andrographolide inhibited JAK2/STAT3 signaling by downregulating the phosphorylation status of STAT3, which in turn decreased the expression of tumor PD-L1 in NSCLC." (PMID 38397437, 2024). "Our study demonstrates that EVs derived from CRC cells promote tumor angiogenesis by regulating the JAK/STAT3/VEGFA pathway in endothelial cells." (PMID 39596828, 2024). "Specifically, LRP1B impacted the survival of tumor cells by modulating the phosphorylation level of the transcription factor STAT3, and consequently regulating the expression of SLC7A11." (PMID 39660409, 2024). "HT29 sh-gp130 xenografts established and grew significantly slower compared to HT29 sh-co xenografts showing a dependence of tumours to gp130/STAT3 signalling activity." (PMID 38600086, 2024). "Other factors present in the tumor microenvironment, such as IL-4, activate the STAT3 signaling pathway in macrophages, leading to their transformation into M2 macrophages." (PMID 38426090, 2024). "GC tumor tissues presented increased expression of activated STAT3, with higher levels recorded in cases involving spread in the peritoneal region." (PMID 39309860, 2024). "While STAT3 is known to reduce the anti-tumor activity of NK cells, it is also reported to be essential for IFNγ production and degranulation of NK cells." (PMID 38891037, 2024). "Such dataset outcomes are consistent with numerous reports that STAT3 influences EMT biomarker levels in tumor cells." (PMID 38019450, 2024).